MIR3677 (microRNA 3677)
Synonyms: hsa-mir-3677; mir-3677
Gene: MicroRNA gene on chromosome 16 (2,270,713 to 2,270,772, forward strand). Ensembl gene ENSG00000266643.
Homologues: Orthologues: chimpanzee MIR3677 (100% identical).